PPARG (peroxisome proliferator activated receptor gamma)
Diseases named in the same sentence as PPARG in open-access papers (continued):
Sharing a sentence is not in itself a finding about the gene and the disease.
sensorineural hearing loss (1 paper, 2018). "The results presented here in a NIHL in vivo model, demonstrate that, pioglitazone, the PPARγ agonist, may represent an effective and innovative therapeutic strategy for hearing loss-related diseases such as sensorineural hearing loss, aging and ototoxicity." (PMID 30349478, 2018).
sialadenitis (1 paper, 2022). Sialadenitis is an infection of the salivary glands. "Taken together, PPARγ activation may mediate the attenuation of sialadenitis in NOD mice caused by the ADF regimen through dampening Th1 responses." (PMID 36430269, 2022).
skin aging (1 paper, 2025). The gradual irreversible changes in structure of skin that occur as a result of the passage of time.. "Taken together, these findings suggest that the coordinated actions of PPARG, ESR1, and IL6 could serve as promising molecular targets of OFSO for counteracting skin aging hair loss disorders." (PMID 41516153, 2025).
skin inflammation (1 paper, 2025). "Network toxicology analysis indicated a low risk of these carboxylic acid compounds inducing skin inflammation, with certain compounds (e.g., 3-phenyllactic acid) potentially exerting positive effects on MMP9 and PPARγ." (PMID 40286213, 2025).
Splenomegaly (1 paper, 2016). Abnormal increased size of the spleen. "Here, we reported that young mice with PPARγ expression at 25% of the normal level showed splenomegaly independent of extramedullary hematopoiesis compared with mice with ≥50% PPARγ expression." (PMID 27221351, 2016). "By contrast, in the current study, younger PPARγ hypomorphic PpargC/− mice developed splenomegaly without changes in the bone architecture or relocation of hematopoiesis to the spleen." (PMID 27221351, 2016).
Tangier disease (1 paper, 2022). "The Tangier disease caused by ABCA1 mutation cannot express ABCA1 protein, and LXRα and PPARγ cannot regulate the reverse transport of cholesterol, which directly proves the regulation of ABCA1 by PPARγ-LXRα pathway." (PMID 36557773, 2022).
tenosynovial giant cell tumor (1 paper, 2024). A tumor usually arising in the synovium of joints, bursa or tendon sheath.
testicular Leydig cell neoplasms (1 paper, 2014). "The indirect pharmacological mode of action produced by PPAR agonists is not unique to the urothelium, and indirect effects have also been seen with PPARγ agonists in the production of rat pancreatic acinar cell tumors and, to some extent, rat testicular Leydig cell neoplasms." (PMID 24427312, 2014).
thymic tumour (1 paper, 2015). "Furthermore, PPARγ-MG KOs had a significant ~4-fold decrease in thymic tumour incidence compared to PPARγ-WT mice in the DMBA Only-treated group (10 ± 5% vs. 40 ± 10%, respectively; p < 0.05)." (PMID 25889730, 2015).
thymoma (1 paper, 2021). A neoplasm arising from the epithelial cells of the thymus. "PPARγ overexpression more than doubled insulin-stimulated thymoma viral protooncogene phosphorylation during low lipid availability." (PMID 34104648, 2021).
tongue cancer (1 paper, 2025). A malignant neoplasm affecting the tongue. "Those hub genes involved in pathways of cancer are Bcl2, EGFR, ESR1, MMP9, PPARG, and MMP2 and those involved in PI3K-Akt signaling pathways are Bcl2, EGFR, CDK2, and MCL1 these genes are considered therapeutic targets for tongue cancer." (PMID 39863836, 2025).
tularemia (1 paper, 2010). Tularemia is an infection caused by the bacterium Francisella tularensis. "Thus, the role of PPARγ in the immunopathogenesis of tularemia should be interpreted with caution as it might have both beneficial and detrimental effects in the outcome of the disease." (PMID 20082697, 2010).
varicocele (1 paper, 2025). A condition characterized by the dilated tortuous veins of the spermatic cord with a marked left-sided predominance. "In conclusion, reduced expression of PPARγ in human ejaculated spermatozoa appears to be influenced by the presence of seminal OS, this could play a role in reproductive pathological conditions associated with OS as varicocele, urogenital infections, or others." (PMID 40001905, 2025). "The main results obtained in this study indicate a reduced PPARγ expression and high levels of F2-IsoPs and RvD1 in cases with varicocele and urogenital infections." (PMID 40001905, 2025). "The impact of varicocele and urogenital infections on sperm PPARγ expression was studied." (PMID 40001905, 2025). "Despite normal sperm parameters, the percentages of sperm with normal morphology and normal vitality were reduced in the presence of varicocele and urogenital infections, suggesting a protective role of PPARγ in the regulation of sperm maturation and morphology." (PMID 40001905, 2025). "At this purpose, both varicocele and urogenital infections likely create an inflammatory environment within the male reproductive tract, which can increase ROS production suppressing PPARγ activity." (PMID 40001905, 2025). "In this study, the expression of PPARγ was evaluated in the spermatozoa of men with normal semen parameters (N), and in men with normal semen parameters affected by pathological reproductive conditions such as varicocele (N + V) or urogenital infections (N + UI)." (PMID 40001905, 2025). "It is also reasonable to suppose that reduced PPARγ activity might contribute to abnormal sperm morphology, since PPARγ shares a similar modular structure with steroid receptors that are under-expressed in men affected by varicocele." (PMID 40001905, 2025). "The PPARγ gene expression was investigated in spermatozoa of 26 normozoospermic men grouped according to their clinical conditions: normal semen parameters (N), normal semen parameters and varicocele (N + V), and normal semen parameters and urogenital infections (N + UI)." (PMID 40001905, 2025). "The aim of this study was to quantify the PPARγ relative mRNA levels in spermatozoa from patients with normal semen parameters (above the 5th percentile according to the WHO), and with normal semen parameters and varicocele or positive semen culture (classified as urogenital infections)." (PMID 40001905, 2025).
visceral leishmaniasis (1 paper, 2024). A severe form of leishmaniasis characterized by irregular bouts of fever, substantial weight loss, swelling of the spleen and liver, and anemia (which may be serious). "On the other hand, monocytes isolated from patients with dermal sequelae of visceral leishmaniasis (post-kala-azar dermal leishmaniasis—PKDL) demonstrated decreased expression of TLR-2/4, simultaneous attenuation of ROS and increased expression of classic M2 markers (CD206, ARG1, and PPARγ)." (PMID 38743668, 2024).
vitamin D deficiency (1 paper, 2023). A nutritional condition produced by a deficiency of VITAMIN D in the diet, insufficient production of vitamin D in the skin, inadequate absorption of vitamin D from the diet, or abnormal conversion of vitamin D to its bioactive metabolites. "In a similar study in mice, vitamin D deficiency was associated with increased expression of adipogenesis-promoting genes such as PPARγ." (PMID 37432159, 2023).
vulvar disease (1 paper, 2021). A non-neoplastic or neoplastic disorder that affects the vulva. "Vulvar tissue patterns of patients with non-malignant vulvar diseases were tested by immunohistochemical expression level for COX-2 and PPARγ for clarifying differences between malignant and non-malignant tissue expression levels." (PMID 33802010, 2021).
xeroderma pigmentosum (1 paper, 2018). Xeroderma pigmentosum (XP) is a rare genodermatosis characterized by extreme sensitivity to ultraviolet (UV)-induced changes in the skin and eyes, and multiple skin cancers. "The authors also found reduced trans-activator function of PPARγ in their xeroderma pigmentosum system, and suggested a model where S112ph by CDK7 activates PPARγ function, in opposition to the repressive S112ph mediated by MAPK signaling." (PMID 29895749, 2018).
Zinc deficiency (1 paper, 2017). A deficiency of the essential metal Zinc; an essential cofactor for many enzymes. "Moreover, PPARG signaling and expression is decreased upon zinc deficiency and PPARG structurally requires zinc ions." (PMID 28303117, 2017).
α-synucleinopathy (1 paper, 2023). "Here we analyze the reported therapeutic effects of PPARs, specifically the gamma isoform (PPARγ), in preclinical PD animal models and clinical trials for PD, and we suggest possible anti-α-synucleinopathy mechanisms acting downstream from these receptors." (PMID 36834679, 2023). "This review critically presents the evidence of the neuroprotective effects of PPARγ in preclinical PD models and patients, and proposes potential anti-α-synucleinopathy effects of PPARγ agonists that may become suitable disease-modifying drugs." (PMID 36834679, 2023).
tumor (997 papers, 2002 to 2026). "PPARG expression was strongly positively correlated with stromal score and cancer-associated fibroblasts (CAFs), but negatively correlated with tumor purity." (PMID 41596281, 2026). "In the luminal subtype, PPARγ positively controls genes associated with tumor cell differentiation, whereas in the basal subtype, high PPARγ activity is linked to tumor progression and immune evasion." (PMID 40806474, 2025). "Conversely, decreased PPARγ expression has been associated with increased tumor-associated macrophages, higher metastasis rates, and reduced survival rates." (PMID 40603870, 2025). "Following efferocytosis, tumor-associated macrophages (TAMs) undergo metabolic reprogramming mediated by Peroxisome proliferator-activated receptor gamma (PPARγ) and Liver X receptor (LXR), leading to their polarization towards an M2-like phenotype." (PMID 41383622, 2025). "Concurrently, EA inhibits adipocyte differentiation while promoting mesenchymal stem cell osteoblast differentiation by suppressing the transcriptional activity of PPARγ, a process that further disrupts tumor-associated metabolic reprogramming." (PMID 40823021, 2025). "By acting as partial agonists of PPARγ, falcarinol and its derivatives inhibit cancer cell proliferation and promote differentiation, suggesting that PPARγ activation is associated with reduced tumor growth and enhanced sensitivity to chemotherapy." (PMID 40699870, 2025). "This suggests that the loss of PPARγ activity acts to promote neoplasia through its ability to induce stromal changes associated with tumorigenesis." (PMID 39195246, 2024). "Cytokines such as IL-4 and IL-13 within the tumor microenvironment regulate the polarization of tumor-associated macrophages (TAMs) through downstream Stat6-dependent inhibition of Arg1, activation of PPARγ, and TSC1-mediated inhibition of mTOR." (PMID 39676873, 2024). "Dysregulation of PPARγ signaling is linked to tumor development in breast and Proteoglycans can influence cell growth by interacting with growth factors via their core proteins or their GAG chains." (PMID 38791477, 2024). "If the loss of PPARG is a defining feature of NMSC tumor–stroma interactions, then it would be important to determine the nature of these early signals to identify potential interventional targets." (PMID 39195246, 2024). "Contrary to the case of repurposing losartan to PAX8 alterations, this fusion promotes tumor progression due to the likely loss of functions of peroxisome proliferator-activated receptor gamma (PPARG)." (PMID 38779099, 2024). "Derivatives of itaconate that are lipid soluble, including 4-octyl itaconate (OI) and dimethyl itaconate (DI), exerted tumor-enhancing effects that were associated with poor patient survival by downregulating PPARγ, with OI having a slightly higher impact." (PMID 38611081, 2024). "Contrary to our results, another study reported that induced PPARγ upregulation is associated with wide TGCT tumor necrosis." (PMID 38882990, 2024). "Higher PPARγ signaling is linked to macrophage polarization in the tumor microenvironment, especially the M2 type." (PMID 38882990, 2024). "Controversially, a germline mutation of PPARG gene is associated with tumour progression in the literature." (PMID 38378472, 2024). "PPARγ is involved in the metabolic reprogramming of neoplastic cells, tumor cell-associated secretions, tumor microenvironment, adaptations, and the host immune response to tumors." (PMID 38882990, 2024). "In the literature, there is also evidence that mutations in the PPARG gene are related to the development of neoplasia." (PMID 38378472, 2024).
tumor (continued). "Recent studies have described that cytoplasmic PPARγ expression is linked to unique tumor criteria that are tissue-dependent and that it is inversely related to nuclear expression; however, the exact mechanism and significance are not fully understood." (PMID 38882990, 2024). "The following year, a study based on Sleeping Beauty confirmed that the insertion of mutations in the PPARγ gene made mice more tumor-aggressive." (PMID 37251321, 2023). "Stromal CD36 loss during tumor progression reflects impairment of PPARγ expression by tumor-derived factors." (PMID 37816052, 2023). "Although substantial evidence suggests that PPARγ activation has a positive effect on tumor suppression, PPARγ has also been implicated in promoting cancer progression in multiple types of tumors." (PMID 38023181, 2023). "The PPARγ-dependent upregulation of FAO also mediates the pro-tumor (also known as M2-like) polarization of tumor-associated macrophages (TAMs)." (PMID 36816914, 2023). "We then studied the relationship between the activated PPARγ pathway and NF-κB pathway in Arf1-deficient tumor cells." (PMID 39872623, 2023). "PPARG has been reported to be expressed in various tumor cells and shows significant association with prognosis in PDAC (p = 0.016)." (PMID 36895481, 2023). "Caspase-1 cleaves peroxisome proliferator-activated receptor gamma (PPARγ), which limits FA oxidation, thereby accumulating lipid droplets and promoting tumor-associated macrophage differentiation." (PMID 37426676, 2023). "Previous studies have shown that PPARβ/δ activation is associated with tumor progression, whereas PPARα and PPARγ activation is associated with tumor suppression." (PMID 37251321, 2023). "Emerging evidence indicates that PPARγ also controls cell proliferation in various other tissues and organs including the breasts, and the dysregulation of PPARγ signaling is linked to tumor development in these organs." (PMID 37185433, 2023). "Previous investigations have implicated that PTGDS influenced tumor progression by modulating PPARγ, MAPK, and STAT3 pathways." (PMID 34743203, 2022). "Important is the multifaceted activity profile of PPARγ agonists in tumor tissues, characterized by antagonizing tumor-associated inflammation, promoting immune response and differentiation of tumor cells." (PMID 35814409, 2022). "In recent decades, substantial evidence indicates that the dysregulation of the PPARγ signal was linked to tumor development in the lungs, colon, and breast." (PMID 36286423, 2022). "Decreased expression of PPARγ has been observed in many tumor types and is usually associated with poor prognosis in cancer patients." (PMID 36326938, 2022). "We find the MMP9+ macrophages to be terminally differentiated tumor-associated macrophages (TAMs) and PPARγ to be the pivotal transcription factor driving their differentiation." (PMID 35933472, 2022). "Overexpression of FABP5 interacts with PPARγ in a coordinated manner to promote malignant progression of tumor including tumor expansion and aggressiveness caused by reduced apoptosis and increased angiogenesis." (PMID 35445019, 2022). "It has been shown that PPARγ is highly expressed in most tumor cells, which is closely linked to cell cycle arrest, differentiation, and apoptosis." (PMID 36286423, 2022). "Early investigations revealed that, in the majority of cases, the activation of PPARβ/δ is linked to tumor progression, whereas PPARα and PPARγ are associated with anti-tumorigenesis." (PMID 33946986, 2021). "In BC cachectic patients, the secretion of miR-155 by tumor cells restored adipocyte metabolism, reducing PPARγ expression levels, and was associated with tumor progression." (PMID 34354950, 2021). "Promotes activation of the peroxisome proliferator-activated receptor γ (PPARγ) in tumor-associated macrophages (TAMs) causing activation to macrophage M2 and tumor growth." (PMID 35095895, 2021).